CDC50B (cell division cycle 50 P4-ATPase accessory subunit B)
Description:
Accessory component of a P4-ATPase flippase complex which catalyzes the hydrolysis of ATP coupled to the transport of aminophospholipids from the outer to the inner leaflet of various membranes and ensures the maintenance of asymmetric distribution of phospholipids. Phospholipid translocation also seems to be implicated in vesicle formation and in uptake of lipid signaling molecules. The beta subunit may assist in binding of the phospholipid substrate (Probable). Can mediate the export of alpha subunits ATP8A1, ATP8B1, ATP8B2 and ATP8B4 from the ER to the plasma membrane.
Synonyms: TMEM30B
Tractability: Antibody: UniProt places it where antibodies can reach, with high confidence; its Gene Ontology location is reachable by antibodies, with high confidence; UniProt predicts a signal peptide or a membrane-spanning region.
Gene: Protein-coding gene on chromosome 14 (61,277,370 to 61,281,761, reverse strand). Ensembl gene ENSG00000182107.
Subcellular location: Cell membrane; Endoplasmic reticulum membrane
Gene Ontology:
Molecular function: aminophospholipid flippase activity; protein binding
Biological process: aminophospholipid transport; endosomal transport; phospholipid translocation; aminophospholipid translocation
Cellular component: endoplasmic reticulum membrane; phospholipid-translocating ATPase complex; plasma membrane; endoplasmic reticulum; membrane
Genetic constraint (gnomAD): Loss-of-function variants: 18 observed, 16.11 expected, observed/expected ratio (o/e) 1.12, 90% interval 0.77 to 1.64. The upper end of that interval is the gene's LOEUF score, 1.64, which puts it in group 6 of 6, group 1 being the genes least tolerant of losing a copy. Missense variants: 408 observed, 379.15 expected, observed/expected ratio (o/e) 1.08, 90% interval 0.99 to 1.17. Synonymous variants: 194 observed, 170.88 expected, observed/expected ratio (o/e) 1.14, 90% interval 1.01 to 1.28.
Homologues: Orthologues: chimpanzee TMEM30B (100% identical), macaque TMEM30B (97% identical), pig TMEM30B (96% identical), rabbit TMEM30B (91% identical), mouse Tmem30b (90% identical), rat Tmem30b (90% identical), dog TMEM30B (89% identical), guinea pig TMEM30B (86% identical), tropical clawed frog tmem30b (58% identical), zebrafish tmem30b (54% identical), Drosophila melanogaster Cdc50 (46% identical), Caenorhabditis elegans chat-1 (42% identical), and 2 more. Paralogues in human: CDC50A (52% identical).
Diseases named in the same sentence as CDC50B in open-access papers:
CDC50B is named in the same sentence as 6 diseases in open-access papers, as found by Europe PMC text mining. Sharing a sentence is not in itself a finding about the gene and the disease.
CDC50B shares sentences with these, for which no sentence is quoted: tumor (2 papers); breast carcinoma (1); clear cell renal cell carcinoma (1); deafness (1); microphthalmia (1); parasitemia (1).